SPARC (secreted protein acidic and cysteine rich)
Diseases named in the same sentence as SPARC in open-access papers (continued):
Sharing a sentence is not in itself a finding about the gene and the disease.
tumor (continued). "However given the limited number of samples analyzed, a more comprehensive multi-center study is under way for evaluating the effect of tumor grade on SPARC and SLIT-2 ELISA results." (PMID 26889680, 2016). "With the exception of the TIC-initiated tumor derived from one non-SPARC transfected cell line, the other 3 TIC-derived tumors all had a similar level of focal expression of the SPARC protein, showing moderate immunoreactivity in approximately 10% of the tumor." (PMID 26783756, 2016). "The tumor from this cell line displayed SPARC mRNA expression below that present in the corresponding SPARC-transfected cell line and parental UROtsa cells, but clearly above the background levels present in tumors generated from the As#6 cell line with and without the vector control." (PMID 26783756, 2016). "Regardless, SPARC is likely a key component in organizing ECM proteins such as TGFBI in the tumor microenvironment and both may be prognostic indicators of chemotherapeutic response." (PMID 27622658, 2016). "Although SPARC is not a tumor-specific protein, its overexpression is associated with tumor growth, metastasis, and aggressiveness." (PMID 27421134, 2016). "It has been suggested that SPARC may influence both tumor stroma formation, through induction of ECM expression and promote cell migration, giving further support to our findings." (PMID 27622658, 2016). "In addition, tumor SPARC is subject to epigenetic silencing through promoter methylation in many cancers." (PMID 27564266, 2016). "A preliminary study showing that SPARC-positive cancer patients had a higher response to an Abraxane®, supports the hypothesis that SPARC mediated accumulation of albumin in tumours increases the effectiveness of albumin-bound paclitaxel." (PMID 26925240, 2016). "Because SPARC mediates albumin transport, it may facilitate entry of albumin-bound paclitaxel into the tumor cells." (PMID 27544129, 2016). "Meanwhile, some laboratory studies on cell lines and animal models showed that SPARC could attenuate the angiogenesis but inhibit the proliferation of tumor, whereas others indicated SPARC to promote cancer development, invasion and metastasis." (PMID 28053291, 2016). "This study showed that SPARC gene was differentially expressed in all the tumor conditions." (PMID 27401257, 2016). "The expression of SPARC in tumor stroma has been associated with a poor prognosis in non-small cell lung cancer and with disease recurrence in breast ductal carcinoma in situ." (PMID 26783756, 2016). "And of the five articles which reported the poor prognostic value of SPARC, one reported that SPARC in the stroma, but not in the tumor, was associated with worse survival." (PMID 26731428, 2016). "In cancer patients, high SPARC protein levels may enhance the tumor concentration of nab-paclitaxel and improve the treatment response." (PMID 27421134, 2016). "Since some of these ligands (such as SPARC) are involved in the control of tumor progression, the regulation of their extracellular concentration by stabilin-1 can result in microenvironmental changes affecting tumor growth." (PMID 27105498, 2016). "This would suggest that the ability to initiate the focal expression of SPARC in the TIC-derived tumors is due to some unknown feature of the tumor environment." (PMID 26783756, 2016). "Conversely, in advanced PCa patients both OPN and SPARC overexpression are associated with poor prognosis and metastatic phenotype, implying that the same ECM proteins can exert different functions at different tumor stages." (PMID 26700622, 2016). "We cannot exclude that due to promiscuous ligand-binding ability of stabilin-1 uptake of unidentified tumor-regulating ligands in addition to SPARC may contribute to overall tumor promoting effect of stabilin-1." (PMID 27105498, 2016). "The role of SPARC in tumor development and metastasis is contextual." (PMID 27564266, 2016).
tumor (continued). "SPARC significantly suppressed carcinogen-induced ROS generation and inflammation while restraining cell cycle progression in cancer cells, thus limiting the increasing demands of the growing tumor cells to new blood vessels." (PMID 27564266, 2016). "What is unknown in the present study is if the focal expression of SPARC is a favorable sign of tumor differentiation or one of tumor progression." (PMID 26783756, 2016). "And the expression of KLF4, a tumor suppressor, could inhibit SPARC expression to restrain the tumor invasion." (PMID 26731428, 2016). "SPARC has been correlated with metastasis based on changes in cell shape, which could promote tumor cell invasion." (PMID 25786138, 2015). "Recent studies revealed that nab-paclitaxel showed promising activity, which might be enhanced by utilizing the binding of albumin to secreted protein, acidic and rich in cysteine (SPARC) and enhanced tumor accumulation of chemotherapeutic agents." (PMID 25859409, 2015). "The inhibition of IRE1α-mediated cleavage of mRNAs encoding the invasion marker SPARC and other ECM candidate targets, as well as of microRNAs functionally associated to tumor invasiveness, could participate to this phenotypic switch." (PMID 26325176, 2015). "Nab-paclitaxel's uptake is facilitated by SPARC, which was highly expressed in the patient's tumor, suggesting that the tumor may have been sensitive to this cytotoxic agent." (PMID 26510912, 2015). "Indeed, TRPS1 and Cath-D co-repress transcription of secreted protein rich in cysteine gene (SPARC), a tumor suppressor in MDA-MB-231 ER− BCC and promote c-MYC and TGFB3 expression." (PMID 26183398, 2015). "A previous study proposed that SPARC may play a key role during the initial steps in the process of tumor invasion and metastasis." (PMID 25859409, 2015). "Moreover, stem cell fibroblasts seem to migrate to primary carcinoma, and we suggest that they were responsible for the release of SPARC to tumor cells." (PMID 26703564, 2015). "Emerging evidence proposes that SPARC produced by host leukocytes, rather than the tumor, determines the assembly and function of tumor-associated stroma via collagen type IV organization." (PMID 25013460, 2014). "Matricellular proteins, including osteopontin, tenascin or SPARC, are gaining increasing attention for their roles in shaping local or metastatic niches to either support or prevent the growth and colonization potentials of tumor cells." (PMID 25331979, 2014). "We and others also found in several tumor models that stabilin-1 is expressed by TAM, leading to the hypothesis that stabilin-1-mediated clearance of SPARC can affect tumor angiogenesis." (PMID 24634660, 2014). "In addition to FN1 and SPARC, other well-established EMT-associated genes are also upregulated in these tumor samples following letrozole treatment including TWIST1, SNAI2, ZEB1, and ZEB2." (PMID 24944582, 2014). "The SPARC is a crucial matricellular protein and may influence the course of various diseases like tumor metastasis and fibrosis." (PMID 25126876, 2014). "SPARC may then facilitate the accumulation of NAB-paclitaxel in the tumor and potentially increase its effectiveness." (PMID 24484617, 2014). "NAB-paclitaxel may act as a “Trojan horse,” with the albumin encapsulation serving to direct the paclitaxel chemotherapeutic agent to tumor cells via binding to SPARC." (PMID 24484617, 2014). "Moreover, a correlation between the expression of SPARC tumor on the deep margin of the lesion and the deep invasion was present (P = 0.016)." (PMID 24396828, 2013). "SPARC, also called osteonectin, is a highly conserved 43-kDa glycoprotein which can be expressed by osteoblasts, endothelial cells, fibroblasts, macrophages, as well as by a variety of tumour cell types." (PMID 24499539, 2013). "However, the tumor suppressive properties of SPARC are highly dependent on various aspects, especially cell phenotype and the tumor microenvironment." (PMID 23123816, 2013).
tumor (continued). "Moreover, the expression of stromal SPARC adjacent to the tumor showed a significant correlation with the high expression of Ki-67 (P = 0.040) and with the histopathologic grading (P = 0.025)." (PMID 24396828, 2013). "Finally a statistical elaboration between SPARC tumor expression and clinicopathological parameters highlighted a direct correlation with the amount of cigarettes daily smoked (P = 0.001) and with histopathological grading (P = 0.05)." (PMID 24396828, 2013). "On this last series it was possible not only to confirm the data of aberrant expression of SPARC in the stroma of the deep layer with a significance even more evident, but also to correlate the high expression of SPARC with the grade of the tumor and proliferation index." (PMID 24396828, 2013). "In addition, an ELISA specific for active TGFβ1 was performed on SPARC+/+ and SPARC−/− tumor lysates." (PMID 22348081, 2012). "Tumor formation was performed in S1 subclone infected by SPARC shRNA virus in nude mice." (PMID 22879971, 2012). "It was proposed that SPARC exerts its anti-proliferative role in primary and metastatic sites at least in part by increasing the collagen content and mechanical stiffness of the fibers surrounding the tumor, thus restricting the growth of the tumor." (PMID 22481923, 2012). "The tumors were dissected, fixed by formalin and embedded by paraffin, then IHC experiments were made, the tumor formed by SPARC shRNA infected cells showed lower SPARC expression, while the tumor formed by control shRNA infected cells showed higher SPARC expression." (PMID 22879971, 2012). "We have reported recently that SPARC can reduce TGFβ activity on the surface of pericytes; we are investigating whether an analogous system is also in place on tumor cells." (PMID 22348081, 2012). "Importantly, although invasion and metastatic incidence and events were increased in SPARC−/− compared to SPARC+/+ mice, as previously reported, losartan normalized tumor progression in SPARC−/− mice to the equivalent of that observed in SPARC+/+ counterparts." (PMID 22348081, 2012). "Tumor formation was performed in high invasive subclone HeLa-1 cells infected by SPARC shRNA." (PMID 23050783, 2012). "Interestingly, SPARC can inhibit the production of TSP1 in endothelial cells; however, the effects of SPARC on the expression of TSP1 in tumor remain elusive." (PMID 22481923, 2012). "Therefore, the inhibition of HSP27 is expected to promote apoptotic signaling, as well as inhibit SPARC-induced tumor cell survival signaling." (PMID 22480225, 2012). "The tissue-normalizing function of SPARC could be extended to cancer with implications for tumour growth, invasion, and metastasis." (PMID 22400028, 2012). "Indeed, in ovarian cancer, SPARC has been shown to sensitize tumor cells to cisplatin therapy and to enhance apoptosis and potentiate sensitivity to the chemotherapeutic agent 5-fluorouracil in colorectal cancer." (PMID 22480225, 2012). "On the other hand there is evidence of a tumor-suppressing role of SPARC." (PMID 22347440, 2012). "However, the role of SPARC in tumor development and metastasis varies because of its context-specific functions (EMT promotion versus inhibition of cell growth)." (PMID 22481923, 2012). "In tumor-bearing Sparc-/- mice there was a reduced macrophage recruitment suggesting that SPARC may have chemotactic activity on macrophages." (PMID 24213109, 2011). "Radiosensitivity and response to 5-fluorouracil and irinotecan in the mouse xenografts, however, was able to be restored by the re-expression of SPARC, while the overexpression of SPARC in CRC xenografts enhanced tumour sensitivity to radiation and chemotherapy." (PMID 21818290, 2011).
tumor (continued). "Taken together, these observations suggest that the efficacy of the native SPARC protein on tumor regression may be blunted when its proteolysis results in the release of different fragments with opposing biological effects." (PMID 22069448, 2011). "This study further examines the mechanism by which SPARC may be promoting apoptosis and identifies a smaller peptide analogue with greater chemosensitizing and tumor-regressing properties than the native protein." (PMID 22069448, 2011). "Co-culturing of the SPARC-transfected cells with wild-type or vector-control xenografts also resulted in fewer activated fibroblasts that were unable to produce enough ECM to support tumour growth." (PMID 21818290, 2011). "In addition to cytokines, macrophages are also a source of extracellular matrix (ECM) proteins, (e.g., macrophage-derived SPARC, osteonectin), which are beneficial to tumor cells in angiogenesis, proliferation, and migration." (PMID 24212647, 2011). "This, together with previous in-vivo studies demonstrating greater tumor regression of xenografts of MIP/SP cells to chemotherapy led us to examine if tumor xenografts overexpressing the N-terminus domain of SPARC also had a heightened sensitivity to chemotherapy." (PMID 22069448, 2011). "The contradictory reports regarding the role of SPARC in cell growth and tumour formation suggest that its effects are cell-type specific and may be dependent on concentration and ECM components." (PMID 20087345, 2010). "Others considered that this suppression might be related to the tumor growth, and SPARC had an antiproliferative function through modulating cell cycle regulatory proteins or growth factors." (PMID 20565704, 2010). "The precise biological and molecular mechanisms through which a reduction in SPARC expression might contribute to improved tumor therapy remain to be investigated." (PMID 20525171, 2010). "SPARC expression in MSC positively correlates with tumor differentiation and lymph node metastasis and may be involved in regulation of production of angiogenesis factor VEGF." (PMID 20565704, 2010). "Our results indicate that SPARC expression inhibits tumour growth in vivo." (PMID 20087345, 2010). "On the basis of these observations, we conclude that endogenous SPARC levels can contribute to the reversion of the malignant phenotype and may, therefore, act as a tumour suppressor in human PDAC cells." (PMID 19920824, 2010). "The SPARC is an ECM protein that influences the ‘soil’ in which tumours develop." (PMID 20087345, 2010). "In contrast, co-culture of fibroblasts in the presence of PDAC cells augmented SPARC expression in fibroblasts, suggesting that high SPARC expression in the tumour stroma may be mainly a result of augmented SPARC expression in stromal fibroblasts." (PMID 19920824, 2010). "Moreover, in tumor xenograft models, the growth of pancreatic and lung cancers in SPARC-/- knockout mice was shown to be significantly enhanced compared with wild-type mice." (PMID 20687958, 2010). "Overexpression of SPARC decreases angiogenesis, which leads to decreased tumour growth." (PMID 20087345, 2010). "In other types of cancer, SPARC functions as a tumor suppressor." (PMID 20525313, 2010). "Overexpression of full-length SPARC significantly reduced tumour size in xenografts." (PMID 20087345, 2010). "In recent years, the role of SPARC as a modulator in the pathogenesis of different malignancies has become increasingly evident and its role in tumorigenesis appears to be complex, dependent on cell type and tumor microenvironment." (PMID 20687958, 2010). "In cancer, the expression pattern of SPARC is variable depending on the tumor types." (PMID 20565704, 2010). "To determine if SPARC siRNA could reduce protumorigenic cellular behaviors associated with SPARC expression, we first determined the effect of decreased SPARC expression on tumor cell invasion." (PMID 20525171, 2010).
tumor (continued). "Therefore, more studies are warranted to better delineate the regulation of SPARC and its role in tumor progression." (PMID 20687958, 2010). "The results in our study showed that SPARC expression in MSC was significantly higher than that in cancer cells and in normal mucosa tissues, and only SPARC expression in MSC was significantly different with clinicopathological parameters including tumor differentiation and lymph node metastasis." (PMID 20565704, 2010). "Besides Brg-1, we also found that SPARC expression and secretion as well as SPARC promoter-driven transcriptional activity were induced by fenretinide in tumor cells." (PMID 20687958, 2010). "Similar to other anti-angiogenic agents, the SPARC peptides induced normalization of blood vessels and thus may enhance drug delivery to the tumor tissue." (PMID 20525313, 2010). "SPARC also directly inhibits endothelial cell binding to the extracellular matrix by modulating extracellular calcium levels, effectively inhibiting blood vessel migration through the tumor stroma." (PMID 20671917, 2010). "The upregulation of SPARC (Secreted Protein Acidic and Rich in Cysteine) after treatment with lenalidomide is particularly interesting given its location at 5q 31–32 and its role as a tumor suppressor with its anti-proliferative, anti adhesion, anti-angiogenic properties." (PMID 19674465, 2009). "The same patient with Stage IV disease and hypermethylation in 95% of CpG sites within the SPARC promoter from samples isolated from the tumour also had an area of the surrounding normal colon examined, and this showed hypermethylation in only 50% of the CpG sites." (PMID 18458674, 2008). "SPARC has also been shown to regulate adhesion and spreading of various types of tumor cells." (PMID 18328103, 2008). "Our digital approach was combined to standard laboratory genotyping experiments to propose a set of validated variants in the secreted protein acidic and rich in cysteine (SPARC) gene, a key factor in cell-matrix interactions and possibly tumour aggressiveness." (PMID 17201911, 2007). "High levels of cytoplasmic SPARC in cancer cells could be seen in a few cases, and the immunoactivity was detected mainly in the cancer cells localized at the tumor-stroma interface, similar to the pattern of laminin-5γ2." (PMID 17187659, 2006). "High expression of the SPARC gene was found in 51 of 55 tumor samples (96.3%)." (PMID 17022822, 2006). "This strongly suggests that SPARC expression is necessary for tumor growth and maintenance, and may be used as a promising prognostic marker in OS." (PMID 17022822, 2006). "Increasing evidence in the literature have suggested that overexpression of SPARC might play a role in many types of tumor, and both tumor and stromal cells within tumor have been shown to express SPARC." (PMID 17187659, 2006). "The antiadhesive properties of SPARC facilitate the invasion and metastasis of tumour cells." (PMID 15558074, 2004). "Furthermore, SPARC has demonstrated antiadhesive properties and displayed diminished adhesive interactions between tumour cells and the extracellular matrix via the reduction of cell–substrate contacts and the promotion of cytoskeletal rearrangement." (PMID 15558074, 2004). "SPARC may be expressed predominantly either in the tumour cells or in the stromal cells depending on the types of malignancies." (PMID 15558074, 2004). "It has been suggested that SPARC may play a key role during the initial steps in the process of tumour invasion and metastasis." (PMID 15558074, 2004). "The signals originating from tumour cells regulate SPARC expression in neighbouring fibroblasts." (PMID 15558074, 2004). "Furthermore, SPARC contributes to tumour progression by inducing EMT via the activation of SNAI237." (PMID 39865173, 2025). "Importantly, SPARC has emerged as a regulator of tumorigenesis, serving as a sensor and integrator of various interactions within the surrounding microenvironment, regulating tumor-stroma interactions." (PMID 40943659, 2025).